MICOS13 (mitochondrial contact site and cristae organizing system subunit 13)
Description:
Component of the MICOS complex, a large protein complex of the mitochondrial inner membrane that plays crucial roles in the maintenance of crista junctions, inner membrane architecture, and formation of contact sites to the outer membrane. Constituent of mature MICOS complex, it is required for the formation of cristae junction (CJ) and maintenance of cristae morphology. Required for the incorporation of MICOS10/MIC10 into the MICOS complex.
Synonyms: C19orf70; MIC13; QIL1; P117; MIC12
Tractability: Antibody: UniProt predicts a signal peptide or a membrane-spanning region. PROTAC: ubiquitination databases record sites on it.
Gene: Protein-coding gene on chromosome 19 (5,678,421 to 5,680,516, reverse strand). Ensembl gene ENSG00000174917.
Subcellular location: Mitochondrion inner membrane
Subcellular location (Human Protein Atlas): Mitochondria; Nucleoplasm
Pathways (Reactome):
Organelle biogenesis and maintenance: Cristae formation
Gene Ontology:
Molecular function: protein binding
Biological process: cristae formation; inner mitochondrial membrane organization
Cellular component: MIB complex; MICOS complex; mitochondrial crista junction; mitochondrial inner membrane; mitochondrion; SAM complex
Genetic constraint (gnomAD): Loss-of-function variants: 19 observed, 17.02 expected, observed/expected ratio (o/e) 1.12, 90% interval 0.78 to 1.63. The upper end of that interval is the gene's LOEUF score, 1.63, which puts it in group 6 of 6, group 1 being the genes least tolerant of losing a copy. Missense variants: 164 observed, 151.26 expected, observed/expected ratio (o/e) 1.08, 90% interval 0.95 to 1.23. Synonymous variants: 61 observed, 61.66 expected, observed/expected ratio (o/e) 0.99, 90% interval 0.8 to 1.22.
Gene-disease validity (ClinGen):
ClinGen rates the evidence that MICOS13 causes each of these diseases.
mitochondrial disease (autosomal recessive): Definitive.
Homologues: Orthologues: chimpanzee MICOS13 (93% identical), macaque MICOS13 (92% identical), mouse Micos13 (87% identical), rat Micos13 (86% identical), pig MICOS13 (86% identical), guinea pig MICOS13 (84% identical), dog MICOS13 (76% identical), tropical clawed frog micos13 (41% identical), zebrafish micos13 (41% identical).
Diseases named in the same sentence as MICOS13 in open-access papers:
MICOS13 is named in the same sentence as 32 diseases in open-access papers, as found by Europe PMC text mining. Sharing a sentence is not in itself a finding about the gene and the disease. The quoted sentences say what the papers report.
liver disease (4 papers, 2016 to 2021). "Two siblings that presented with severe mitochondrial encephalopathy and recurrent bouts of liver disease were identified to have a homozygous mutation in the MICOS13 gene (coding for MIC13 protein, also known as QIL1) (c.30-1G>A), resulting in a functionally null allele." (PMID 34356047, 2021).
Cerebellar atrophy (3 papers, 2016 to 2020). Cerebellar atrophy is defined as a cerebellum with initially normal structures, in a posterior fossa with normal size, which displays enlarged fissures (interfolial spaces) in comparison to the foliae secondary to loss of tissue. "In the present study, we found a new variant in MICOS13 in a patient with liver failure, microcephaly, cerebellar atrophy, and pulmonary congestion associated with mitochondrial complex deficiencies and mtDNA depletion." (PMID 32749073, 2020). "Mutations in MICOS13 (aka QIL1) cause severe infantile mitochondrial disease characterised by failure to thrive, microcephaly, truncal hypotonia, spasticity and cerebellar atrophy, lactic acidosis and 3-methylglutoconic aciduria (3-MGA)." (PMID 32858900, 2020).
Encephalopathy (2 papers, 2020 to 2021). Encephalopathy is a term that means brain disease, damage, or malfunction. "Our findings suggest that the novel c.13_29del (p.Trp6Profs*71) MICOS13 variant causes hepato‐encephalopathy with MTDPS." (PMID 32749073, 2020).
mitochondrial DNA depletion syndrome (1 paper, 2020). The mitochondrial DNA (mtDNA) depletion syndrome (MDS) is a clinically heterogeneous group of mitochondrial disorders characterized by a reduction of the mtDNA copy number in affected tissues without mutations or rearrangements in the mtDNA. "In the present study, whole‐exome analysis using next‐generation sequencing identified a novel MICOS13 variant in a case exhibiting mitochondrial DNA depletion syndrome (MTDPS)." (PMID 32749073, 2020).
cancer (1 paper, 2025). A tumor composed of atypical neoplastic, often pleomorphic cells that invade other tissues. "MICOS13, involved in mitochondrial structure, affects metabolism and apoptosis, linking it to cancer progression." (PMID 39783847, 2025).
MICOS13 also shares sentences with these, for which no sentence is quoted: Mitochondrial encephalopathy (4 papers); infection (3); Arrhythmia (2); cardiomyopathy (2); cyst (2); deficiencies (2); leukemia (2); microcephaly (2); mitochondrial disease (2); Barth syndrome (1); breast carcinoma (1); cardiac arrhythmias (1); Cognitive impairment (1); congenital toxoplasmosis (1); Failure to thrive (1); heart hypertrophy (1); hepatopathy (1); Hyperglycemia (1); Hypoglycemia (1); lactic acidosis (1); Listeria infection (1); liver failure (1); Mitochondrial myopathy (1); pancreatic cancer (1); Parkinsonism (1); pulmonary congestion (1); toxoplasmosis (1).